TRPM3 (transient receptor potential cation channel subfamily M member 3)
Diseases named in the same sentence as TRPM3 in open-access papers (continued):
Sharing a sentence is not in itself a finding about the gene and the disease.
Hypertension (1 paper, 2025). The presence of chronic increased pressure in the systemic arterial system. "To further investigate the association between TRPM3 expression and BP regulation, we used a model of AngII-induced hypertension." (PMID 41031400, 2025). "Trpm3-KO mice showed a ≈5% BP reduction and resistance to angiotensin II-induced hypertension." (PMID 41031400, 2025). "Therefore, analysis of the vascular phenotype in Trpm3-KO mice can provide insights into the channel’s potential contribution to hypertension development." (PMID 41031400, 2025). "Remarkably, although Trpm3-KO mice did not develop hypertension after AngII treatment, their vascular response to AngII-induced constriction was unaffected." (PMID 41031400, 2025).
medulloblastoma (1 paper, 2019). A malignant, invasive embryonal neoplasm arising from the cerebellum. "A 203 bp region of the CpG island from the promoter region of the TRPM3 gene was PCR amplified from bisulfite converted genomic DNA of the medulloblastoma cell lines." (PMID 30944042, 2019). "CpG island at the TRPM3/MIR204 promoter locus seems to be not methylated in Group 3 / Group 4 medulloblastomas based on the data from the Illumina 450 K array and bisulfite sequence analysis done on Group 3 medulloblastoma cell lines for the CpG island in the TRPM3/MIR204 promoter region." (PMID 30944042, 2019).
mucolipidosis type IV (1 paper, 2015). A lysosomal disease characterized by psychomotor delay, progressive visual impairment, and achlorhydria. "Regarding the eye, one of them deals with mucolipidosis type IV (MLIV) and another indicates that mutant TRPM3 expression is associated with cataractogenesis and glaucoma." (PMID 26818117, 2015).
Neurodevelopmental delay (1 paper, 2023). "In the present study, we report a de novo missense variant in the ion transport domain of TRPM3 in a child with neurodevelopmental delay and manifestations of CP." (PMID 37684057, 2023). "Hence, our report adds evidence for the association of the variant c.3376A > G in TRPM3 with neurodevelopmental delay and is the first to document a variant in TRPM3 in an individual with CP." (PMID 37684057, 2023).
ocular coloboma (1 paper, 2020). "Subsequently, mutation of the human gene for microRNA-204 (miR-204) that is located within an intron of the TRPM3 gene (reminiscent of TRPM1 and miR-211) has been shown to underlie an inherited form of retinal dystrophy and ocular coloboma." (PMID 32070426, 2020). "Ocular co-expression of TRPM3 and miR-204 is upregulated by the paired box 6 transcription factor (PAX6) and mutations in all three corresponding genes underlie inherited forms of eye disease in humans including early-onset cataract, retinal dystrophy, and coloboma." (PMID 32070426, 2020).
ovarian carcinoma (1 paper, 2022). A malignant neoplasm originating from the surface ovarian epithelium. "In our study, inorganic ion trans-membrane transports for calcium (TRPM3), sodium (SLC family) and potassium (KCNK1) were significantly up-regulated in the metastatic ovarian cancer samples compared to the primary ones, which were in accord with previous researches." (PMID 35915456, 2022).
pancreatic disorders (1 paper, 2021). "If true, then modulating TRPM3 activity might be a potential future clinical application in treating acidosis induced pancreatic disorders." (PMID 33603674, 2021).
Photophobia (1 paper, 2024). Excessive sensitivity to light with the sensation of discomfort or pain in the eyes due to exposure to bright light. "When mRNA levels of Crebbp, Trpm3, Zmynd8 and Akt1 were compared between the two sexes, female photophobia mice showed significant lower levels than that of males." (PMID 39390364, 2024).
prediabetes (1 paper, 2022). "We found two susceptibility loci in MRPS6/SLC5A3 genes associated with 2hPG, six loci in LINC01648, MATN1, CRAT37, and SLCO3A1 genes associated with HbA1C, and five loci in TRPM3/TMEM2 and MLYCD/OSGIN1 correlated to BMI in Hainan prediabetes." (PMID 35299963, 2022).
Pruritus (1 paper, 2021). Pruritus is an itch or a sensation that makes a person want to scratch. "We found that Hist and 5-HT evoked similarly intense pruritus in Trpm3+/+ and Trpm3−/− mice, as we observed in case of cheek injection, as well." (PMID 33130130, 2021). "Although direct activation of TRPM3, similar to TRPV1, resulted exclusively in nociception and not itch, these results cannot exclude that TRPM3 signaling can also contribute to the sensory transduction of pruritus, as has been described for TRPV1." (PMID 33130130, 2021). "However, the role of TRPM3 in the development of pruritus has not been studied yet." (PMID 33130130, 2021).
thyroid cancer (1 paper, 2023). "Treatment with 5′-aza-2-deoxycytidine (5′AZA), a demethylating agent, for 24 h led to a significant increase of miR-204-5p and its host gene (TRPM3) transcripts in TPC-1 and BCPAP cells, suggesting that DNA methylation mediates miR-204-5p silencing in thyroid cancer cell lines." (PMID 37445942, 2023).
Wilms tumor (1 paper, 2021). An embryonal neoplasm characterized by the presence of epithelial, mesenchymal, and blastema components. "For Family 2 (Wilms tumor), the top-five ranked genes were FAM8A1, TRPM3, PAH, PCK1, and PCK2." (PMID 34624066, 2021).
tumor (20 papers, 2010 to 2025). "Similarly, the variants detected within the TRPM3 gene (rs1329774 and rs4745058) in our study are likely linked to downregulated gene expression and thus are significantly associated with tumour progression." (PMID 40535770, 2025). "Based on these findings, TRPM3 deficiency may play an important role in KIRC tumor progression, providing a therapeutic strategy for KIRC treatment." (PMID 36588677, 2022). "Importantly, elevated expression of TRPM3 in RCC is significantly associated with larger tumor size, higher TNM stage and poor prognosis, coincident with high expression of circPRRC2A in larger tumors and more severe TNM stages." (PMID 32292503, 2020). "TRPM3 regulates heat sensation, secretion, neurotransmitter release, iris constriction, and tumor promotion." (PMID 40305282, 2025). "The results showed that TRPM3 mRNA expression was lower in tumor tissues relative to peri-tumor tissues." (PMID 36588677, 2022). "circ-PRRC2A acts as a sponge molecule, adsorbing miR-514a-5p and miR-6776-5p to prevent the degradation of the tissue-specific oncogene TRPM3 mRNA, and promote angiogenesis and tumor metastasis." (PMID 34616746, 2021). "The mammalian TRPM3 gene hosts a non-coding microRNA gene specifying miR-204 that serves as both a tumor suppressor and a negative regulator of post-transcriptional gene expression during eye development in vertebrates." (PMID 32070426, 2020). "GSEA demonstrated that sh-circPRRC2A resulted in a TRPM3-mediated EMT, cell adhesion and angiogenesis are the prominent causes of tumor cell metastasis." (PMID 32292503, 2020). "Here, we showed that TRPM3 was upregulated in larger implantation tumor tissues and knockdown of circPRRC2A suppressed the expression of TRPM3." (PMID 32292503, 2020). "Six hits in five genes [AK3 (rs378117), TRPM3 (rs1329774 and rs4745058), CDH4 (rs2427043), LINC00504 (rs76228864), and GRIN2D (rs76754767)] were associated with a risk of tumour progression, whereas variants in HPGD (rs45593131) and RC3H2 (rs2792999) were suggested as protective factors." (PMID 40535770, 2025). "Although variants rs10166768 (C>G) with LRP1B and rs200093832 within TRPM3 reached a p-value below the significance threshold only in the PTC tumor samples and not the PTC blood samples compared to the 1KGP controls, MAFs did not suggest somatic mutations." (PMID 39770638, 2024). "TRPV4 and TRPM3 have been shown positively related to tumor progression." (PMID 36588677, 2022). "TRPM3, on the other hand, affects the tumor progression of ccRCC by regulating autophagy." (PMID 35721115, 2022). "Moreover, the loss of TRPM3, TRPV1, TRPV2, and TRPML1 expression has been proposed as a negative prognostic marker for GBM patients, because of their significant and progressive down-regulation as the tumor grade increases." (PMID 33928077, 2021). "Moreover, we examined the expression of TRPM3 in tumor tissues of nude mice." (PMID 32292503, 2020). "Subsequently, a biotin- coupled miRNA pulldown experiment determined that circPRRC2A may sponge both miR-514a-5p and miR-6776-5p, thereby increasing TRPM3 and inducing epithelial-mesenchymal transition (EMT) and tumor angiogenesis in RCC." (PMID 32292503, 2020). "Since a definite role for TRPM3 in tumorigenesis has not been reported, a detailed study examining TRPM3’s potential tumor suppressor role and its synergistic effect with miR-204 (if any) will be subject of future investigations." (PMID 23285024, 2012).
cancer (18 papers, 2010 to 2025). A tumor composed of atypical neoplastic, often pleomorphic cells that invade other tissues. "Conversely, the Kaplan–Meier analysis revealed that high TRPM3 mRNA expression levels were significantly associated with an improved prognosis and increased OS of all examined patients with various cancer subtypes." (PMID 40535770, 2025). "A large-scale database analysis revealed that the level of the TRPM3 transcript was decreased in the majority of cancer tissues." (PMID 40535770, 2025). "DNA methylation in the promoter CpG island of the TRPM3/miR-204 gene can lead to downregulation observed in certain cancers while activated STAT3 can bind to regulatory regions of TRPM3, reducing miR-204 expression." (PMID 39199587, 2024). "The tissue enhanced TRPA1 (intestine, urinary bladder, and vagina) and group-enriched TRPM3 (brain, kidney, and retina) also exhibited perturbed expression in corresponding cancer types." (PMID 35614079, 2022). "Six genes were found to be implicated in cancer etiology/progression/clinical outcomes with high degree of certainty: MMP1, DDX4, TRPM3, DPP6, KCNA1, and MUC17." (PMID 32625238, 2020). "Uncoupling of expression of TRPM3 and miR-204 is obviously important for development of ccRCC and probably exists in other types of cancers where TRPM3 is upregulated." (PMID 27438705, 2016). "Moreover, we also revealed several tissue or group-enriched genes (such as TRPM8, TRPA1, and TRPM3) in cancer." (PMID 35614079, 2022). "Since the genomic localization of miR-204 is within the TRPM3 gene, the TRPM3-miR-204 axis may play role in cancer development." (PMID 34512152, 2021). "With the role of TRPM3 in cancers, the TRPM3-miR-204 feedback loop may be important to prevent progression of oncogenic transformation and may also exist widely in physiological situations." (PMID 27438705, 2016). "Interestingly, TRPM3 is a member of the transient receptor potential melastatin (TRPM) family, which has also been reported to be associated with cancer progression." (PMID 24321270, 2013). "Tobacco related genes, such as USP9X, ARID2, MLL4, TRPM3 and UNC13C, exactly showed no mutations in buccal mucosal cancer cell lines with no risk-habits of tobacco smoking or chewing." (PMID 36611830, 2022). "The other three differentially mutated genes, including SAGE1, TRPM3, and ADAMTS7, have not been implicated in HCC, but in some other cancers." (PMID 27246981, 2016).
neurodevelopmental disorder (6 papers, 2023 to 2025). A behavioral and cognitive disorder with onset during the developmental period that involves impaired or aberrant development of intellectual, motor, or social functions. "Several studies in the literature have shed light on the association between mutations in the TRPM3 gene and neurodevelopmental disorders." (PMID 39639951, 2024). "Pathogenic variants in TRPM3 are associated with neurodevelopmental disorder with hypotonia, dysmorphic facies, and skeletal anomalies, with or without seizures (NEDFSS; OMIM:620224)." (PMID 37684057, 2023). "To date, 10 TRPM3 variants have been published in the medical literature in children with neurodevelopmental disorders, but our report is the first to describe CP manifestations in an individual with a pathogenic TRPM3 variant." (PMID 37684057, 2023). "Three patients harbored four predicted PL/P variants in other genes causing neurodevelopmental disorders (GRIN2B, MADD, TRPM3 and ZEB2), leading to alternative diagnoses for them." (PMID 38566815, 2024).
neurological disorders (3 papers, 2021 to 2025). "Despite its essential roles in pain signaling and neurological disorders, the mechanisms underlying TRPM3’s temperature- and ligand-induced activation and inhibition remain poorly understood." (PMID 39896661, 2025). "Finally, various genetic alterations in the TRPM3 gene were linked to several neurological disorders in human patients." (PMID 33732703, 2021). "This study provides a framework for understanding the thermal sensing mechanisms of temperature-sensitive ion channels and offers a structural foundation for developing TRPM3-target therapeutics for pain and neurological disorders." (PMID 39896661, 2025). "Together, these structural insights pave the way for the development of selective TRPM3 modulators to address critical unmet needs in pain management and neurological disorders." (PMID 39896661, 2025). "The TRPM3 channel is a key nociceptor for sensing noxious heat and a promising therapeutic target for pain treatment and neurological disorders such as epilepsy." (PMID 39896661, 2025).
inflammation (2 papers, 2021 to 2022). Aberrant reaction of the microcirculation characterized by movement of fluid and leukocytes from the blood into extravascular tissues. "To assess a potential impact of functional TRPM3 upregulation during bladder inflammation, we compared female wild-type and Trpm3−/− mice twenty-four hours after injection of CYP." (PMID 35008533, 2021).
immune dysfunction (1 paper, 2022). "The recent finding of impaired TRPM3 ion channel and Ca2+ mobilisation in NK cells, provides further evidence of immune dysfunction in ME/CFS." (PMID 35986236, 2022).
peripheral neuropathy (1 paper, 2025). A disorder affecting the peripheral nervous system. "Addressing these translational challenges will be critical for the safe and effective deployment of M1R and TRPM3 modulators as therapies for peripheral neuropathy." (PMID 40806522, 2025). "This review highlights mitochondrial and Ca2+ signaling imbalances in DSPN and presents M1R antagonism and TRPM3 activation as promising neuro-regenerative strategies that shift treatment from symptom control to nerve restoration in diabetic and other peripheral neuropathies." (PMID 40806522, 2025). "By addressing core deficits in bioenergetics, axonal degeneration, and synaptic connectivity, M1R/TRPM3 modulation represents a significant paradigm shift in the treatment of peripheral neuropathy—one that redefines therapeutic success in terms of regeneration and long-term functional recovery." (PMID 40806522, 2025).
TRPM3 also shares sentences with these, for which no sentence is quoted: bladder cancer (2 papers); Hypomagnesemia (2); Kabuki syndrome (2); respiratory disease (2); age-related macular degeneration (1); Age-related nuclear cataract (1); aniridia (1); Anxiety (1); aortic valve calcification (1); aphakia (1); Becker muscular dystrophy (1); bladder overactivity (1); Cerebellar atrophy (1); cerebral palsy (1); choroid plexus papilloma (1); colorectal cancer (1); congenital cataracts (1); coronary artery disease (1); Crohn disease (1); cutaneous squamous cell carcinoma (1); cystic kidney disease (1); cystic kidneys (1); depression (1); head and neck cancer (1); Hypercalciuria (1); Hypermagnesemia (1); Hypermetropia (1); Hypocalcemia (1); Hypotonia (1); Impaired glucose tolerance (1).
A further 29 diseases each share a sentence with TRPM3 in 1 paper.